LRRC46 (leucine rich repeat containing 46)
Description:
Required for normal spermatogenesis and male fertility. Plays an important role in sperm flagellum biogenesis.
Synonyms: MGC16309
Tractability: Antibody: the Human Protein Atlas places it where antibodies can reach. PROTAC: ubiquitination databases record sites on it.
Gene: Protein-coding gene on chromosome 17 (47,831,634 to 47,837,719, forward strand). Ensembl gene ENSG00000141294.
Subcellular location: Cell projection, cilium, flagellum
Subcellular location (Human Protein Atlas): Plasma membrane; Basal body; Nuclear bodies; Primary cilium
Gene Ontology:
Biological process: sperm flagellum assembly; spermatogenesis
Cellular component: sperm flagellum; motile cilium; sperm midpiece
Genetic constraint (gnomAD): Loss-of-function variants: 16 observed, 25.84 expected, observed/expected ratio (o/e) 0.62, 90% interval 0.42 to 0.94. The upper end of that interval is the gene's LOEUF score, 0.94, which puts it in group 3 of 6, group 1 being the genes least tolerant of losing a copy. Missense variants: 294 observed, 384.08 expected, observed/expected ratio (o/e) 0.77, 90% interval 0.69 to 0.84. Synonymous variants: 142 observed, 155.36 expected, observed/expected ratio (o/e) 0.91, 90% interval 0.8 to 1.05.
Homologues: Orthologues: chimpanzee LRRC46 (99% identical), macaque LRRC46 (94% identical), pig LRRC46 (79% identical), dog LRRC46 (78% identical), rabbit LRRC46 (78% identical), guinea pig LRRC46 (70% identical), mouse Lrrc46 (70% identical), rat Lrrc46 (64% identical), tropical clawed frog lrrc46 (30% identical), Drosophila melanogaster TbCMF46 (17% identical), Drosophila melanogaster Ppr-Y (16% identical), Caenorhabditis elegans T05H4.3 (14% identical). Paralogues in human: CEP97 (23% identical), LRRC9 (20% identical), LRGUK (19% identical), DNAAF1 (18% identical), DNAAF11 (17% identical), LRRC43 (17% identical), LRRC49 (17% identical), DRC3 (16% identical), LRRC23 (16% identical), LRRCC1 (16% identical), LRRIQ3 (15% identical), PPP1R42 (15% identical), and 1 more.
Diseases named in the same sentence as LRRC46 in open-access papers:
LRRC46 is named in the same sentence as 8 diseases in open-access papers, as found by Europe PMC text mining. Sharing a sentence is not in itself a finding about the gene and the disease. The quoted sentences say what the papers report.
Ciliary Dyskinesia (2 papers, 2022). "Several genes (ARMC4, SP2, LRRC46, RSPH9, and ZMYND10) assigned to associations are involved in primary ciliary dyskinesia (PCD), an autosomal recessive inherited disease." (PMID 35052452, 2022).
Familial prostate cancer (1 paper, 2022). Prostate carcinoma that has developed in relatives of patients with a history of prostate carcinoma. "Previous studies have indicated Lrrc46 was found as a novel candidate susceptibility gene in familial prostate cancer (PCa), high-grade serous ovarian cancer (HGSOC), Glioblastoma, and Nasopharyngeal carcinoma (NPC)." (PMID 35955660, 2022).
male infertility (1 paper, 2022). The inability of the male to effect fertilization of an ovum after a specified period of unprotected intercourse. "Our study suggests that LRRC46 is an essential protein for sperm flagellum biogenesis, and its mutations might be associated with MMAF that causes male infertility." (PMID 35955660, 2022).
LRRC46 also shares sentences with these, for which no sentence is quoted: Cognitive impairment (1 paper); glioblastoma (1); Infertility (1); nasopharyngeal carcinoma (1); serous ovarian cancer (1).